CD34 (CD34 molecule)
Diseases named in the same sentence as CD34 in open-access papers (continued):
Sharing a sentence is not in itself a finding about the gene and the disease.
leukemia (continued). "Acquisition of such genetic alteration transforms a normal Lin–CD34+CD38– HSC into a CML-initiating cell/leukemia stem cell, with a proliferative advantage and bias toward myeloid differentiation." (PMID 38440231, 2024). "These xenografts have proved a better engraftment of human AML and yielded more heterogeneity in leukemia stem cell populations including CD34+ CD38+ cell populations, suggesting the critical importance of the microenvironment in vivo." (PMID 39272967, 2024). "Leukemic stem cells are a subpopulation of leukemia cells characterized by the CD34 + CD38- phenotype, and are considered to be resistant to standard treatment." (PMID 38666914, 2024). "The combination of apigenin with LY294002 for treatment of CD34+CD38−/low leukaemia cells, including leukaemia stem cells, induced apoptosis in these cells associated to caspase activation, mitochondrial dysfunction, and downregulation of Bcl-xL and NF-κB." (PMID 38612718, 2024). "High MYC and CD34 expression define T-ALL cells with leukemia-initiating cell (LIC) properties in activated NOTCH1-driven T-ALL5,17,66,67." (PMID 38352301, 2024). "Among the AML stem cell population, CD34+/CD38- arethe only ones capable of inducing leukemia in vivo." (PMID 38818079, 2024). "According to the cell surface marker profile, LSCs are CD34+/CD38−/CD123+ malignant cells that initiate leukemia in NOD/SCID mice with unfractionated AML." (PMID 37692500, 2024). "Leukemic stem cells are a subpopulation of leukemia cells characterized by the CD34+CD38- phenotype considered to be resistant to standard treatment." (PMID 37754227, 2023). "It has been demonstrated that CD34+ leukemia stem cells display a high level of autophagic flux, and, more importantly, TKI treatment, as the flip side, stimulates autophagy responsible for leukemia stem cell survival and establishment of drug resistance." (PMID 36876044, 2023). "In this work, Linear programming computational models were used to establish the diagnosis of various leukemia subtypes, such as Bone Marrow CD34, Bone Marrow, AML, PB, and PBSC CD34." (PMID 37812613, 2023). "Accurate and efficient classification and quantification of CD34+ cells are essential for the diagnosis and monitoring of leukemia." (PMID 38131753, 2023). "The CD34+CD38− leukemia cell population holds leukemia stem cells (LSCs) accountable for therapy failure in acute myeloid leukemia (AML) and, therefore, new therapies are needed for eradicating LSCs without harming healthy hematopoietic stem cells (HSCs)." (PMID 36984844, 2023). "Second, it provides critical insights into the prognosis of leukemia patients, with higher percentages of CD34+ cells in AML patients correlating with poorer outcomes than those with lower percentages." (PMID 38131753, 2023). "Thirdly, CD34+ cell classification plays a pivotal role in monitoring the response of leukemia patients to treatment." (PMID 38131753, 2023). "CSCs were first identified in leukemia, and researchers found that only implantation of CD34 + CD38-acute leukemia (AML) cells into immunodeficient mice triggered leukemia 7)." (PMID 37213675, 2023). "The combination of varying features of antigen expression is more informative in predicting survival, where CD34(+)/CD38(−)/CD123(+) representing the leukemia stem cell phenotype has prognostic relevance." (PMID 36808479, 2023). "The combination of synergistically induced cell death in both CD45+ leukemia blasts and CD34+ stem/progenitor cells (patients #26 and #28)." (PMID 37088806, 2023). "In AML, the first study of CSCs was published in the late twentieth century, in which Bonnet and Dick isolated a subset of CD34+/CD38− leukemia cells." (PMID 36879313, 2023).
leukemia (continued). "In patients with AML in whom U5 snRNP200 cell surface expression was detected on bulk CD34+ malignant cells, U5 snRNP200 was also present on immunophenotypically defined leukemia stem cells." (PMID 37872381, 2023). "Detection of CD34+ cells, cells expressing CD34, is crucial for monitoring diseases such as leukemia and hematopoietic stem cell transplantation." (PMID 38131753, 2023). "Hussein recommends a basic immunohistochemical panel including CD45 (for lymphoid malignancies), AE1/AE3 pankeratins (for most carcinomas), S100 (melanomas), and CD34 (vascular neoplasms and leukemias)." (PMID 37142464, 2023). "The results of this study confirmed that these CD34+CD38- cells were responsible for initiating leukemia." (PMID 37241170, 2023). "In relapsed acute myeloid leukaemia (AML), a phase I trial using Plerixafor demonstrated efficacy in overcoming stromal-leukaemia protection against targeted therapy, by mobilising CD34+CD38− leukaemia cells to the periphery." (PMID 36780103, 2023). "Perriello and coworkers analyzed a large cohort of NPM1-mutated AML patients and confirmed that CD123 is highly expressed in these leukemias, particularly at the level of the CD34+/CD38− cell population." (PMID 36769040, 2023). "went on to further show that TWIST1 was most highly expressed in the putative leukemia stem cell (LSC) compartment in AML (CD34+CD38-) and that its expression in LSCs was higher than in normal CD34+CD38- HSCs." (PMID 37600794, 2023). "CD34-positive CSCs have been identified in leukemia, breast cancer, lung cancer, and other types of tumors." (PMID 37241170, 2023). "The issue of the superiority of molecular chimerism on CD34+ cells over other methods for leukemia relapse prediction is still unsolved." (PMID 36950550, 2023). "Various surface markers, such as CD93, CD69, and CD36, have been found to demarcate distinct subpopulations of immunophenotypically sorted HSC-like cells (CD34+CD38−) that differ in leukemia initiating activity and cell cycle status." (PMID 37653425, 2023). "To mimic the BM microenvironment we co-cultured CP-CML CD34+ cells with the stroma cell line HS-5 to investigate the stroma-leukaemia cell interaction and measure the effectiveness of our inhibitors." (PMID 38031192, 2023). "Validation using samples from 13 leukemia patients demonstrated a high level of agreement with flow cytometry in quantifying CD34+ cells." (PMID 38131753, 2023). "The DNAm levels at three individual CG dinucleotides (CpG sites) in the genes MYO1D, STK17A, and SP140 correlated with CD34+ cell numbers in mobilized peripheral blood and with blast counts in leukemia." (PMID 37370186, 2023). "In the CD34+CD38–TIM3+CD99+ leukemia stem cell–enriched (LSC-enriched) fraction, RUNX1mut LSCs (SU371) exhibited higher expression of IL-3RA compared with matched RUNX1wt LSCs (SU524, SU770)." (PMID 37581927, 2023). "We used upstream regulator analysis and the activation z-score to identify changes in gene expression in MLLr leukemia cells compared with huCB-derived CD34+ HSPCs." (PMID 37833915, 2023). "Leukemia is diagnosed when more than 20% of immature cells (blasts) in the bone marrow contain the CD34+ marker." (PMID 38131753, 2023). "This rare drug-resistant cell is responsible for maintaining leukemia and is usually enriched in CD34+CD38−cells." (PMID 37392305, 2023). "As a result of the abrogation of this effect, they found that the CD34+CD38+ fraction of seven AML samples initiated leukemia in immunodeficient animals." (PMID 37735675, 2023). "Results indicated that LY/Api synergistically enhanced apoptosis in leukemia cells, particularly CD34+CD38− leukemia cells." (PMID 36984844, 2023). "It was efficient against both multidrug resistant CML blasts and CD34+/CD38− leukemia stem cells coming from CML patients." (PMID 35892900, 2022). "Impact of leukemia stem cell frequency (CD34/CD38/CD123) at diagnosis on overall survival in 80 acute myeloid patients." (PMID 35530356, 2022).
leukemia (continued). "Accordingly, examining the top 50 differentially expressed genes in our dataset showed a higher proportion of genes, associated with stemness in the literature, and upregulated in the CD34‐positive leukemias (P = 0.0225, Fisher's exact test)." (PMID 35271751, 2022). "The leukemias were CD34+CD10highCD19+ positive with V(D)J clonal markers and repopulated secondary transplanted mice." (PMID 35115489, 2022). "Already within 24 h, BK124.1 induced apoptosis in CD34+/CD38− leukemia stem cells from all the patients." (PMID 35892900, 2022). "The ALL cells were mostly CD19+ and partially CD34+, with an expression profile similar to that of human pro-B leukemia cells." (PMID 36335100, 2022). "Genes of the pathway were found to be up-regulated in certain leukemia-derived quescent hemopoietic stem cells expressing CD34 in contrast with dividing cells supplied by the normal population (Graham, Vass, Holyoake, & Graham, 2010)." (PMID 36176292, 2022). "It was reported that WT1 had a consistent up-regulation with CD34 in acute leukemia cells and also had a simultaneous down-regulation when leukemia cells were differentiated into mature cells." (PMID 36500358, 2022). "Preclinical studies found that PF-913, an inhibitor of SMO, can decrease the proportion of CD34+ leukemia cells, induce dormant LSCs into the cell cycle, reduce leukemia initiation, and exert synergistic effects with cytarabine (AraC)." (PMID 35865470, 2022). "The expression of genes in this gene set is positively regulated in quiescent CD34 + cells from some leukemia." (PMID 36176292, 2022). "The abundance of TCA enzymes was unexpectedly even higher post metformin treatment, excluding the well-known OXPHOS-inhibiting activity of metformin as the responsible mechanism in killing CD34+ leukemia cells." (PMID 35444236, 2022). "A previous study, using reverse phase protein array (RPPA) of 121 selected protein targets, identified differences in the protein profile between AML-SCs and the bulk leukemia and leukemic CD34+ cells from adult AML samples." (PMID 35892824, 2022). "Several markers have already been linked to certain types of CSCs (breast cancer: CD44+/CD24−/ALDH+; leukemia: CD34+/CD8−; liver: CD90+; pancreas: CD44+/CD24+/ESA+; epidermal surface antigen)." (PMID 35659296, 2022). "CD34 is a biomarker of the most immature phenotype in clinical leukemia and its expression is progressively lost as the cells mature and differentiate." (PMID 36500358, 2022). "For instance, BM MSCs co-cultured with leukaemia cell lines had different degree of stemness (CD34+CD38− or CD34+CD38+ or CD34− cells) upregulated differentially with the expression of sets of genes." (PMID 35629139, 2022). "As it has been previously demonstrated that increased c-Mpl expression of CD34+ cells increases leukemia potential, it remains to be determined in future clinical studies if the increased c-Mpl is predominantly of the c-Mel-del isoform." (PMID 36229456, 2022). "In total, 20 primary AML bone-marrow samples were collected and used for the isolation of primary CD34+ leukemia blasts, where CD34+ is a well-characterized biomarker of leukeima stem and progenitor cells." (PMID 35581670, 2022). "Pioneering studies functionally characterised LSCs as a rare subset of the immature CD34+/CD38- population which is capable of initiating leukaemia in immunodeficient mice." (PMID 35223487, 2022). "In leukemia, a CD38‐negative CD34‐positive phenotype has been associated with increased adherence, dormancy, stem‐like features, and therapy resistance." (PMID 35271751, 2022). "For leukemias with bimodal CD34 expression, we found a positive correlation between the percentage of leukemic cells in the CD34‐positive subpopulation and the EOI MRD level (r = 0.34, P = 0.0254, n = 42, Spearman's rank correlation)." (PMID 35271751, 2022).
leukemia (continued). "Using the differentially expressed genes as seed proteins in a PPI network analysis revealed 10 networks significantly altered in CD34‐positive vs CD34‐negative leukemias." (PMID 35271751, 2022). "Leukemia is now considered to be a stem cell disease with its characteristic refractory nature being blamed on a rare population of CD34+/CD38- LSCs." (PMID 35530356, 2022). "In accordance with the findings, knocking down RUNX1 inhibited leukaemia cells growth in both human CD34+ cells transduced with MLL‐AF9 and the MLL‐AF9 mouse model." (PMID 36467848, 2022). "A trend of improved leukemia-free survival and decreased relapse was observed in recipients of a graft with a higher number of CD34 cells (adjusted p = 0.09 and p = 0.07, respectively)." (PMID 36313879, 2022). "Although the pAML20 leukemia was categorized as CD34 positive (>5% CD34 positive AML cells), only 8.6% of the leukemic blasts were CD34 positive." (PMID 35892824, 2022). "The sensitivity of the method in patients with CD34+ leukemia was shown to be comparable to that of PCR assays for the amplification of leukemia-specific transcripts or mutated DNA sequences." (PMID 35252010, 2022). "As with the chemotherapy cohort, AZA+Pembro treatment was associated with downregulation of leukemia-associated genes (FLT3, CD34)." (PMID 36099049, 2022). "Co-expression of BMI1 and BCR-ABL in human cord blood CD34+ cells induces leukemia that can be propagated serially in immunodeficient mice with a bias towards lymphoid blast crisis." (PMID 35650206, 2022). "Unfortunately, most patients treated with TKs, such as dasatinib and imatinib, experience leukemia cell persistence in CML because the leukemia stem cells (CD34 + CD38-) enter the G0 phase, in which the cells become quiescent, and can thus survive." (PMID 36080390, 2022). "The normal hematopoiesis reference contains bone marrow mononuclear cells (BMMCs) and CD34+ enriched BMMCs and the Leukemia data contains single cells from MPAL patients." (PMID 35906531, 2022). "Six stages of leukemia differentiation-arrest categories based on CD34, CD117, CD13, CD33, MPO, and HLA-DR expression were identified in two independent cohorts of 2087 and 1209 AML patients." (PMID 35973983, 2022). "We show that CBX2 is overexpressed in AML cells compared to CD34+ cells and to differentiated monocytes and macrophages, highlighting its possible function as a leukemia-driving oncogene." (PMID 35681235, 2022). "To showcase the potential value of BMOs for studying leukemia treatments, we tested the capacity of BMOs as a supportive environment for CD34+ leukemic blasts." (PMID 35818479, 2022). "In particular, sample leukemia stem cells from patient 12, who had imatinib‐resistant ALL bearing multiple mutations, including T315I, were isolated by CD34‐positive sorting and treated with a single dose of PMIBcr/Abl‐R6 for 24 h." (PMID 35239999, 2022). "The CD34‐positive leukemias showed upregulation of genes involved in cytokine signaling, positive regulation of cell migration and cell adhesion, TGF‐beta signaling, axonal guidance, and negative regulation of apoptosis." (PMID 35271751, 2022). "Like CD34‐positive leukemia‐initiating AML cells we find ROBO4 significantly overexpressed in CD34‐positive ALL samples, but we also find other axonal growth guidance genes upregulated, such as EFNB1 and EPHA7." (PMID 35271751, 2022). "In preclinical studies, leukemia cell lines expressing high or minimal CD34 were incubated with anti-CD34-conjugated SPIONs." (PMID 34727233, 2021). "Np9 protein levels correlated with the number of stem/progenitor cells in leukaemia patient samples but was undetectable in CD34+ hematopoietic stem cells from healthy donors." (PMID 34055625, 2021). "CD123 expression on NPM1mut cells was already reported by our group while characterizing NPM1mut CD34+CD38− leukemia-initiating cells in xenograft experiments." (PMID 33525388, 2021).
leukemia (continued). "Primitive CD34+/CD38− HSPCs were suggested to be leukemia-initiating cells for RUNX1-RUNX1T1, PML-RARα, and KMT2A-MLLT3 AML." (PMID 33803739, 2021). "Taken together, our data demonstrate that labelling of leukemia-derived EVs with CD34 antibody and analysis with FT-FCM allows to quantify CD34+ EVs from peripheral blood of leukemia patients." (PMID 35008226, 2021). "We assessed the expression level of CD34 on leukemia cells treated with PBS or BM-MSC-exos by FCM and found that BM-MSC-exos increased the population of LSCs." (PMID 33789743, 2021). "Leukemia’ (mononuclear cells isolated from bone marrow of patients with confirmed leukemia); ‘CD34+GFs’ (pure CD34+ cells stimulated to undergo clonal expansion in culture)." (PMID 34132194, 2021). "Relative to quiescent CD34+, JH+Total in substrate-replete permeabilized cells was ~2 fold higher in PBMC, CD34+GFs and primary leukemia, consistent with higher cellular mitochondrial density." (PMID 34132194, 2021). "In general, CD34+CD38− AML cell populations display a higher leukemia-initiating cell frequency than CD34+CD38+ AML cell populations." (PMID 34012921, 2021). "The results also showed that the down-regulation of miR-155 mediated by anti-miR-155 induced further apoptosis than the control group in CD34+ CML cells which is consistent with the oncogenic function of miR-155 in leukemia stem cells." (PMID 33907541, 2021). "Application of the platform to MUTZ3 leukemia cells revealed a marked reduction in cellular m6A levels as CD34+ leukemic progenitors differentiate to CD14+ myeloid cells." (PMID 34734208, 2021). "For comparison, we also profiled KMT2A localization in untransformed human CD34+ hematopoietic stem and progenitor cells (HSPCs), in H1 human embryonic stem cells and in the K562 leukemia cell line, each of which lacks KMT2A translocations." (PMID 34663924, 2021). "CSCs were first identified in a leukemia model, in which CD34+CD38− leukemic cells showed the characteristics of bone marrow hematopoietic stem cells." (PMID 34671679, 2021). "We tested this approach using tetraspanin CD81 as a pan-vesicular marker and CD34 as a marker for leukemia-derived EVs." (PMID 35008226, 2021). "Initial studies suggested that CSCs in leukemias (LSCs) are restricted to the CD34+CD38- phenotype, shared with normal HSCs (hematopoietic stem cells), though this statement has been redefined." (PMID 33801964, 2021). "The authors found that ‘Mettl3′ is normally expressed in CD34+ hematopoietic stem/progenitor cells (HSPCs) but aberrantly expressed in leukaemia cells as compared to the other tumour-types." (PMID 34207299, 2021). "As seen in the AML cell lines, calculated fractional OXPHOS was decreased in CD34+GFs and primary leukemia, entirely consistent with low fractional OXPHOS being required for hematopoietic clonal expansion." (PMID 34132194, 2021). "This study overexpressed and knocked down RUNX1 expression in THP-1 human leukemia cells and CD34+ hematopoietic stem/progenitor cells to investigate the biological functions affected by dysregulated RUNX1." (PMID 34434964, 2021). "CD34, an immaturity marker, usually expressed in leukemia cells is universally used as it unequivocally establishes the immature nature of these cells." (PMID 33773558, 2021). "Phenotypically defined leukemia stem cells (CD34 + CD38-CD123 + ) and the remaining stem/progenitor cells (CD34 + CD38-CD123-) showed no heightened activity of signaling networks." (PMID 34040147, 2021). "We transplanted human malignant leukemia cell lines, human CD34+ HSPC and human T cells, into zebrafish embryos." (PMID 33707624, 2021). "Np9 protein expression was shown to be restricted to a subset of leukaemia patient samples (28/50 – mixed leukaemia patients) and only detected in one of 22 healthy CD34+ haematopoietic stem cell samples tested in a separate study." (PMID 34055625, 2021).